BRCA2 (BRCA2 DNA repair associated)
Diseases named in the same sentence as BRCA2 in open-access papers (continued):
Sharing a sentence is not in itself a finding about the gene and the disease.
breast cancer (continued). "The BRCA2 mutation did not affect survival in patients with breast cancer (HR = 1.30)." (PMID 32322271, 2020). "Reporting a family history of PCa, via his father, and breast cancer in his mother and sister, it was not surprising that this patient carries a pathogenic germline BRCA2 stop-gain mutation (rs80359031; c.7988A > T; p.Glu2663Val) confirmed to predispose carriers to BRCA-associated cancers." (PMID 32392735, 2020). "A recent meta-analysis by Akdeniz and colleagues computed the relative risk of contralateral breast cancer development as 2.68 (95% CI 1.69–3.65) for c.1100delC mutation carriers versus noncarriers (which was fully comparable with that in BRCA2 mutation carriers: RR = 2.75; 95% CI 1.77–4.29)." (PMID 33322746, 2020). "Other frequently mutated genes in breast cancer, including Brca1 and Brca2, are not mutated." (PMID 32793490, 2020). "This is postulated to explain why women haploinsufficient for BRCA2 might be predisposed to breast cancer without loss of their functional BRCA2 allele." (PMID 33147438, 2020). "Consistent with the subtyping in our clinical trial samples, few BRCA1 germline mutation related breast tumors in TCGA database are immunomodulatory (7% versus 21% of TNBC from non-carriers) and most BRCA2 germline mutation related breast cancers do not classify as TNBC (12 out of 15, 80%)." (PMID 32164626, 2020). "It has also been postulated that any observed association may be due to the use of tamoxifen for the prevention and treatment of breast cancer rather than a consequence of a BRCA1 or BRCA2 pathogenic variant per se." (PMID 32698099, 2020). "Among the tumors reported in DM BRCA2 families, the most frequent was BC, with a percentage of 76.2%, followed by bBC, male breast cancer (MBC), CC, pancreatic cancer (PAC), and LEU with a percentage of 4.8%." (PMID 33287145, 2020). "Interestingly, ATM c.2289T>C (p.F763L), along with two other variants currently classified as likely benign, BRCA2 c.2926_2927delinsAT (p.S976I) and RAD51D c.251T>A (p.L84H), were determined to be associated with African American breast cancer risk when compared to ethnic-specific controls." (PMID 32866190, 2020). "Furthermore, mutations in moderate-penetrance genes such as BRCA1 interacting protein C-terminal helicase 1 (BRIP1), ataxia telangiectasia mutated (ATM), partner and localizer of BRCA2 (PALB2), and checkpoint kinase 2 (CHEK2) are associated with a two-fold increased risk of developing breast cancer." (PMID 33027908, 2020). "In our study, it indicated an overall 18.4% (17.6% before age 50 years) prevalence of deleterious BRCA1/BRCA2 mutations in high‐risk women diagnosed with DCIS, supporting the presence of an in situ phase of carcinogenesis in the development of at least some BRCA‐associated breast cancer." (PMID 30652428, 2019). "Indeed, susceptibility variants have been found to modify the risk of breast cancer development associated with the BRCA1 and BRCA2 mutations, thereby accounting for the variation in breast cancer penetrance observed for these mutations in different human families." (PMID 30901340, 2019). "In the 64 samples with history of familial breast cancer, BRCA2 exon 1 deletions were found in three cases, deletions of exon 11 in one case, deletion of exon 23 in two cases, exon 17 and exon 26 were deleted in one case each, and two samples presented BRCA2 ex22–24 deletions." (PMID 30630528, 2019).
breast cancer (continued). "The clinical characteristics of breast cancer in patients with the BRCA1 L63X mutation might not differ from those caused by other BRCA1 or BRCA2 mutations, except the subtype and nuclear grade of the resultant cancer." (PMID 31143373, 2019). "Interestingly, BRCA1-, but not BRCA2-, deficient breast cancer was associated with higher PD-L1 (CD274) expression compared to BRCA-proficient breast cancers in both WSI and TCGA cohorts (PBRCA1 = 5.6 x 10−6 and 0.014, respectively." (PMID 31022191, 2019). "Interestingly, BRCA1-, but not BRCA2-, deficient breast cancers were observed to be associated with higher expression of PD-L1 and PD-1, and increased abundance of tumour-infiltrating immune cells involved in adaptive immune response." (PMID 31022191, 2019). "Hereditary breast cancers constitute about 5–10% of all BC cases but pathogenic variants in the high-risk (RR ≥ 4) breast cancer susceptibility genes BRCA1 [OMIM 113705] and BRCA2 [OMIM 600185] account for approximately 50% (0.7–29% BRCA1 and 1.5–25% BRCA2) of all hereditary breast cancers." (PMID 31013702, 2019). "However, comparison of BRCA2-associated and non-BRCA2-associated human breast cancers has shown that BRCA2 mutation does not increase aneuploidy in human cancer." (PMID 30930946, 2019). "Thus, we evaluated the association between reproductive, hormonal, and lifestyle risk factors and mammographic density among women with a strong family history of breast cancer but no BRCA1 or BRCA2 mutation." (PMID 31242899, 2019). "In addition, the UGM can be used to screen many breast cancer-associated genes, such as BRCA1, BRCA2, PTEN, BRIP1, etc., provides better accuracy, robustness and efficiency, the method of identification differentially expressed genes in high-throughput sequencing." (PMID 31865918, 2019). "While the identification of a BRCA pathogenic variant constitutes a clear benefit for probands and their relatives, a proportion of at-risk families do not present pathogenic variants in BRCA1 or BRCA2 and their genetic risk of breast cancer remains unexplained." (PMID 31780696, 2019). "The observed lack of effective treatments for ER-positive BRCA2-associated breast cancer requires attention, and future research needs to be conducted to evaluate the contribution of newer treatments, including platinum-based chemotherapy, oophorectomy and PARP inhibitors." (PMID 30723304, 2019). "Among variant-positive males (N = 81), 2 (2.5%) had breast cancer (BRCA1 c.5266dupC and BRCA2 c.4471_4474delCTGA) and 6 (7.4%) had prostate cancer (two men with BRCA1 c.5266dupC and one man each with BRCA1 c.68_69delAG, BRCA2 c.2808_2811delACAA, BRCA2 c.5946delT, and BRCA2 c.4716_4717delinsAAAGACC)." (PMID 31892343, 2019). "Moreover, women with a BRCA2 mutation without breast cancer should be counselled on the poor prognosis associated with BRCA2-associated breast cancer when making cancer risk reduction decisions." (PMID 30723304, 2019). "Interestingly, BRCA1-, but not BRCA2-, deficient breast cancers were associated with increased expression of PD-L1 and PD-1, higher abundance of tumour-infiltrating immune cells, and enrichment of T cell-inflamed signature." (PMID 31022191, 2019). "Similarly, a Breast Cancer Cluster Region has been described at the end of BRCA2 (c.7394-c.8904)." (PMID 31771539, 2019). "Furthermore, using data from 651 breast cancer patients in Southern China, one BRCA1 pathogenic variant (c.981_982delAT) and three BRCA2 pathogenic variants (c.3109C>T, c.7436_7805del370, and c.9097_9098insA) were analyzed and reported as Chinese founder mutations." (PMID 31143373, 2019). "All above results demonstrated that the methylation of BRCA2 led to its diminished expression, which caused incomplete suppression of RAD51 thus elevating the expression of RAD51, and hence an unfavorable outcome of breast cancer, especially ER-positive breast cancer." (PMID 31506496, 2019).
breast cancer (continued). "Despite the small sample size, the prospective nature of the analysis along with the ability to adjust for potential confounders suggests that RANKL is likely not a circulating biomarker of breast cancer risk among women with an inherited BRCA1 or BRCA2 mutation." (PMID 31069010, 2019). "As expected based on PD-L1 and PD-1 expression and immune infiltrate profile, BRCA1-, but not BRCA2-, deficient breast cancers were associated with higher T cell-inflamed signature in WSI (P = 1.9 x 10−7 and 0.072, respectively) and TCGA (P = 8.0 x 10−3 and 0.95, respectively)." (PMID 31022191, 2019). "The typical breast cancer prognostic factors, including grade, tumour size and nodal status, may not be typical for women with BRCA2 mutations." (PMID 30723304, 2019). "Given that carriers of germline BRCA1 or BRCA2 alterations are more likely to develop breast cancer, it is arguable that mastectomy may be indicated instead of breast-conserving surgery in all carriers to prevent local recurrence in the remaining breast tissue." (PMID 30174725, 2018). "On Dec 5, 2016, we did another PubMed search for studies of patients who carried a BRCA1 or BRCA2 mutation and their prognosis, using the following search terms: “(BRCA) AND (survival or prognosis or outcome or mortality) AND (breast neoplasms or breast neoplasm or breast cancer or breast tumour)”." (PMID 29337092, 2018). "A meta-analysis of cumulative risks for contralateral breast cancer in BRCA1/2 mutation carriers with a first breast cancer showed a cumulative 10-year incidence rate of 27% and 19% for contralateral breast cancer in BRCA1 and BRCA2 mutation carriers, respectively." (PMID 29176636, 2018). "Moreover, several studies showed that high rate and long history of consanguinity, commonly observed in developing countries, decrease breast cancer incidence rate by decreasing the frequency of mutations in high penetrant breast cancer genes such as BRCA1 and BRCA2." (PMID 30594178, 2018). "Women with germline BRCA1 or BRCA2 mutations are recommended to undergo salpingo-oophorectomy bilateral (prophylactic oophorectomy, RRSO) to reduce their risk of developing ovarian cancer (and breast cancer), usually by age 40 or after the completion of child bearing." (PMID 29389895, 2018). "Previous studies and meta-analyses have reported inconsistent effects of BRCA1 and BRCA2 mutations on the outcomes of early breast cancer with better, worse, and similar outcomes for patients with a BRCA1 or BRCA2 mutation compared with patients with sporadic breast cancer." (PMID 29337092, 2018). "We did not write specifically about BRCA1 or BRCA2, but “When analyzing your samples, we have discovered findings indicating that there could be a hereditary cause of your breast cancer." (PMID 29082482, 2018). "PALB2 may also act independently from BRCA2 to regulate the metastasis of the breast cancer cells." (PMID 29321957, 2018). "However, an earlier study from the same country that included 72 unrelated patients with positive family history of breast and/or ovarian cancers or with an early onset breast cancer reported higher carrier rates; deleterious BRCA1 and BRCA2 mutations were reported in 12.5%." (PMID 29409476, 2018).
breast cancer (continued). "In breast cancer for example, mutations in the BRCA1 and BRCA2 genes are more commonly found, with one Nigerian study identifying mutation rates of 7.9% for BRCA1 and 3.1% for BRCA2—far higher than in the cancer genome atlas (TCGA), where these are 1.3 and 1.5% respectively." (PMID 30234014, 2018). "Similarly, a few published works also report earlier age of breast cancer onset in women with a double mutation for both BRCA genes while, to our knowledge, there are no similar data concerning a double mutation involving the K3326X BRCA2 variant." (PMID 29346284, 2018). "Recent data suggest approximately 10% of young or familial TNBC patients with no BRCA1 or BRCA2 mutation carry inherited deleterious mutations in other breast cancer predisposition genes, particularly in genes involved in HRR such as PALB2, BARD1, RAD51C, RAD51D, and BRIP1." (PMID 29108297, 2017). "Furthermore, R-loops accumulate in human cells depleted of DNA repair factors that act during replication, such as those involved in the FA/BRCA pathway, that is in the tumor suppressor and breast cancer-susceptibility genes BRCA1 and BRCA2 or the Fanconi anemia (FA) factors FANCD2, FANCA or FANCM." (PMID 28653981, 2017). "Almost 2000 variants have been found in the two genes (BRCA1 and BRCA2) and, for numerous; it is yet not recognized whether or not they enhance prevalence of breast cancer." (PMID 28969709, 2017). "This is reflected by guidelines on breast cancer risk management in BRCA1/BRCA2 carriers, which do not give clear recommendations for women with a previous diagnosis of ovarian cancer, but support discussion of the option of risk-reducing breast surgery with women on a case-by-case basis." (PMID 28780755, 2017). "There is also promising data that determinants for breast cancer might perform in a different way for carriers of BRCA1 or BRCA2 variants than for females lacking hereditary vulnerability because of these genes." (PMID 28969709, 2017). "Both G5337A and A3199G polymorphisms present in BRCA1 and BRCA2 genes respectively, have not yet been reported as deleterious mutations (i.e. mutations directly involved in the development of breast cancer), and in consequence they should be considered as benign polymorphisms." (PMID 29021639, 2017). "In both groups, the vast majority had breast cancer diagnosis, with only two cases of ovarian cancer (one with a mutation in each BRCA gene, both novel variants) and two cases with both breast and ovary cancers (both with a mutation in BRCA2), all of them in the novel variant group." (PMID 28947987, 2017). "It is estimated that known breast cancer susceptibility loci including BRCA1 and BRCA2 account for approximately 20% of familial risk, with the remaining variation caused by mutations with low-moderate penetrance that may be inherited in a subtype specific manner." (PMID 28241424, 2017). "The cumulative risk for breast cancer by age 70 has been reported to 45–60% for BRCA1 mutation carriers and 27–55% for BRCA2 mutation carriers with a corresponding risk for ovarian cancer of 31–59% and 6–16.5% for BRCA1 and BRCA2 mutation carriers, respectively." (PMID 28096903, 2017).
breast cancer (continued). "The All Breast Cancer in Malmö (ABiM) study, a well-characterized, population-based, prospectively collected cohort of 273 breast cancer patients, diagnosed during the period of 2007–2009 at a single institution, was retrospectively analyzed for the presence of germline BRCA1 and BRCA2 mutations." (PMID 28120249, 2017). "We have shown that tumour promoter methylation within our target suppressor gene panel is commonly observed in familial and particularly BRCA2 male breast cancers suggesting aberrant hypermethylation may be a significant driver in MBCs carrying prognostic information." (PMID 28893223, 2017). "Several FA genes (FANCD1/BRCA2, FANCN/PALB2, FANCJ/BRIP1, FANCO/RAD51C, and FANCS/BRCA1) are high- or moderate-risk breast or ovarian cancer susceptibility genes and previous studies have connected also heterozygous FANCM mutations with breast cancer predisposition." (PMID 28702895, 2017). "Additionally the vast majority of older women with familial breast cancers with good prognostic markers and good prognosis do not carry pathogenic BRCA2 mutations." (PMID 27087880, 2016). "In addition, a number of population studies have revealed that a large proportion of breast cancer patients with a BRCA1 or BRCA2 germline mutation have no history of the disease in the family." (PMID 27129401, 2016). "We have collated the results of screening with either annual mammography or mammography with MRI in female BRCA2 mutation carriers in Manchester and Oslo and use a Manchester control group of BRCA2 mutation carriers who had their first breast cancer diagnosed without intensive screening." (PMID 27087880, 2016). "None of the SNPs were associated with overall breast cancer risk for BRCA2 mutation carriers." (PMID 27117709, 2016). "However, a recent meta-analysis including breast cancer patients who are BRCA2 mutation carriers indicated no survival differences compared to patients without BRCA2 mutations." (PMID 27195161, 2016). "The majority of families with smaller aggregations of breast cancer do not yet have demonstrable underlying genetic defects and the majority of carriers of pathogenic mutations in BRCA1 and BRCA2 do not have strong aggregation of breast cancer in their families." (PMID 27087880, 2016). "Crossover designs would ultimately only provide evidence on the sequence of applying carboplatin-olaparib or capecitabine in BRCA1- or BRCA2-mutated breast cancers but not on whether the regimen targeting the BRCA defect is better than a control treatment." (PMID 27323902, 2016). "Studies have shown that tamoxifen might also be effective in BRCA1 and BRCA2 mutation carriers in respect to reducing CBC risk consistent with our finding of risk reductions regardless of family history of breast cancer." (PMID 27400983, 2016). "However, many women with a family history of breast cancer, including many who carry BRCA1 or BRCA2 mutations, never develop breast cancer." (PMID 26538066, 2015). "Interestingly, the distribution of BRCA1, BRCA2 and ATM rare germline truncations with their somatic mutations across cancer types varies with the high frequency of ATM in prostate, lung and stomach cancers, and BRCA1 and BRCA2 germline events in ovarian and breast cancers." (PMID 26689913, 2015). "Indeed, 40-50 % of women with a BRCA1 or BRCA2 mutation do not develop breast cancer by 70 years of age." (PMID 26538066, 2015). "Furthermore our findings are in keeping with a previous study which examined the association of tissue composition with mammographic density in high breast cancer risk patients undergoing risk-reducing mastectomy, including nine BRCA1 and BRCA2 mutation carriers." (PMID 26110820, 2015). "This current Singapore study, based on 359 Asian breast cancer patients prospectively accrued from a risk-assessment clinic, has identified ER-negativity, TNBC status and a FH of HBOC as predictive factors to increase the likelihood of detecting BRCA1 and BRCA2 mutations." (PMID 26221963, 2015).